SERPINC1 (serpin family C member 1)
Diseases named in the same sentence as SERPINC1 in open-access papers (continued):
Sharing a sentence is not in itself a finding about the gene and the disease.
pulmonary embolism (15 papers, 2016 to 2025). The obstruction of the pulmonary artery or one of its branches by an embolus, sometimes associated with infarction of the lung. "This article will present a case study of a patient with pulmonary embolism resulting from a mutation in the serpin family C member 1 (SERPINC1) gene responsible for AT III, causing type I hereditary AT III deficiency." (PMID 39093784, 2024).
venous thromboembolism (15 papers, 2013 to 2026). Occlusion of the lumen of a vein by a thrombus that has migrated from a distal site via the blood stream. "M313T in SERPINC1 presenting transient antithrombin deficiency and multiple venous thromboembolisms." (PMID 38093370, 2023). "CONCLUSIONS: SERPINC1 gene analysis benefits asymptomatic family members, especially child-bearing women, by informing venous thromboembolism prevention strategies and guiding anticoagulant choice in cases involving heparin-binding site mutations." (PMID 41888834, 2026). "Nevertheless, the molecular mechanism of SERPINC1 in the development of venous thromboembolism deserves further exploration." (PMID 34783290, 2021). "Previously, miR-200c-3p, which was downregulated in hibernating black bear plasma to prevent venous thromboembolism during prolonged immobility, was reported to target SERPINC1." (PMID 34783290, 2021).
nephrotic syndrome (14 papers, 2001 to 2025). A collection of symptoms that include severe edema, proteinuria, and hypoalbuminemia; it is indicative of renal dysfunction. "Previous studies have identified a relationship between SERPINC1 and several kidney diseases, including nephrotic syndrome and acute kidney injury." (PMID 37744355, 2023).
Disseminated intravascular coagulation (12 papers, 2006 to 2025). Disseminated intravascular coagulation is characterized by the widespread activation of coagulation, which results in the intravascular formation of fibrin and ultimately thrombotic occlusion of small and midsize vessels. "Anti‐thrombin III (AT, SERPINC1) was previously investigated as a treatment for bacterial sepsis and associated disseminated intravascular coagulation (DIC)." (PMID 37534622, 2023).
lupus (12 papers, 2013 to 2025). "In the previous study, urine levels of ORM1 and SERPINC1 were elevated in newly diagnosed LN patients compared with healthy controls (HC) and systemic lupus erythematosus (SLE) patients without nephritis." (PMID 37744355, 2023).
hepatocellular carcinoma (10 papers, 2012 to 2026). A malignant tumor that arises from hepatocytes. "In liver cancer, previous studies identified SERPINC1 as an important target affecting the prognosis and disease stratification of patients with hepatocellular carcinoma." (PMID 38923313, 2024). "SERPINC1 is an important serine protease inhibitor which has also been investigated as a biomarker in other malignancies, including hepatocellular carcinoma and central nervous system lymphomas." (PMID 39194522, 2024). "SERPINC1 also has been reported as a potential candidate biomarker for detection of hepatocellular carcinoma." (PMID 38923313, 2024). "SERPINC1 expression could be detected in the three lines of human endothelial cells and in HepG2 human hepatoma cells, being this expression more robust in HepG2 than in hAECs, hCAECs, or hCMECs." (PMID 30319401, 2018).
thrombotic disease (10 papers, 2008 to 2025). The formation of a blood clot in the lumen of a vessel or heart chamber; causes include coagulation disorders and vascular endothelial injury. "Thus, our results suggest that an intensive search for the rs121909567 (SERPINC1; ATBp3) founder mutation might be an important factor for the assessment of thrombotic disease susceptibility among the Roma population." (PMID 34765649, 2021). "Thus, our results suggest the need for an intensive search for the rs121909567 (SERPINC1; ATBp3) founder mutation, which might be an important factor for the assessment of thrombotic disease susceptibility among the Roma population." (PMID 34765649, 2021). "Thrombotic disorders commonly involved mutations in PROC (27%), PROS1 (12%), SERPINC1 (9%), ADAMTS13 (5%), and JAK2 (3%)." (PMID 40488813, 2025).
diabetes (9 papers, 2009 to 2025). "It has been reported that increased plasma levels of APEX1, CD55, PSME2, and SERPINC1 are significantly associated with hypertension, and increased plasma levels of APEX1, CD55, GGCT, KRT17, PSME2, and SERPINC1 are associated with diabetes." (PMID 41156831, 2025).
Hypertension (9 papers, 2014 to 2025). The presence of chronic increased pressure in the systemic arterial system. "This proteoglycan binds to and modulates the effects of several proteins, including heparin-dependent serine protease inhibitors such as antithrombin III (AT3, SerpinC1) and protein C inhibitor (PCI, PAI-3, SerpinA5), both of which we found increased in urinary exosomes of hypertensive patients." (PMID 28562335, 2017).
Obesity (9 papers, 2013 to 2025). Accumulation of substantial excess body fat. "Interestingly, rs121909567 (SERPINC1) (ATBp3 mutation) multiplicatively interacted with CAD, CKD, cancer, DM, depression, migraine, and obesity." (PMID 34765649, 2021). "Some others, such as SERPINC1, coagulation factor XII (involved in contact activation pathways), and protein C (PROC), are involved in the coagulation/fibrinolysis pathways, which are known to be activated in OA, as well as in obesity." (PMID 35606786, 2022).
ischemic stroke (7 papers, 2018 to 2023). A stroke disorder caused by obstruction of blood flow to the brain, due to thrombotic (local blood clot formation) or embolic (due to a blood clot or other material traveling from another site) event. "In the symptomatic AT deficiency with SERPINC1 gene test cohort, ischemic stroke showed a significant association with the detection of pathogenic variation on SERPINC1 gene test, which was 100% in the current study." (PMID 35720094, 2022). "The patients with SERPINC1 variant-related ischemic stroke were divided into two groups with embolic infarction patterns (n = 4) or episodes associated with large artery disease (n = 3)." (PMID 35720094, 2022). "The SERPINC1 gene test was useful in determining the cause of AT deficiency-related arterial thrombosis, especially ischemic stroke." (PMID 35720094, 2022). "Reduced levels of SERPINC1 that we found in the CBS-deficient patients in the present study were also observed in Han Chinese ischemic stroke patients." (PMID 31242583, 2019). "In this regard, we propose a diagnostic algorithm for SERPINC1-associated ischemic stroke." (PMID 35720094, 2022). "Even though selection bias could occur, we assumed that the ischemic stroke patients could also have the pathogenic SERPINC1 variants." (PMID 35720094, 2022). "We propose the diagnostic flow of SERPINC1-related ischemic stroke." (PMID 35720094, 2022). "Future prospective or large cohort studies on the SERPINC1 gene test and ischemic stroke are warranted." (PMID 35720094, 2022). "We evaluated the utility of the SERPINC1 gene test in ischemic stroke, an important clinical type of arterial thrombosis." (PMID 35720094, 2022). "Our study is the first report about the utility of the SERPINC1 gene test in ischemic stroke, an important clinical type of arterial thrombosis." (PMID 35720094, 2022). "This study first showed the utility of the SERPINC1 gene test in arterial thrombosis, especially ischemic stroke." (PMID 35720094, 2022).
lung carcinoma (7 papers, 2019 to 2026). "Moreover, from the gene chip data of the GEO database, we observed a higher Serpinc1 expression level in metastatic patients with lung cancer, suggesting a positive association between Serpinc1 gene expression and tumor metastasis." (PMID 35992834, 2022). "In lung cancer, the researchers demonstrated in vitro and in vivo that overexpression of SERPINC1 promotes the proliferation and distant metastasis of lung cancer cells." (PMID 38923313, 2024). "It has been shown that reducing SERPINC1 expression can be an effective treatment for lung cancer." (PMID 38203636, 2023). "Kaplan–Meier’s plots revealed a significant inverse correlation of Serpinc1 gene expression and overall survival in lung cancer patients, especially in patients with lung adenocarcinoma, but there was no significant inverse correlation in patients with lung squamous cell carcinoma." (PMID 35992834, 2022). "Consequently, we showed the antitumor effects of the combined agents in vivo and identified for the first time the important role of Serpinc1 in lung cancer progression and treatment, including cell proliferation, apoptosis, migration, and invasion possibly via the Pi3K/AKT pathway." (PMID 35992834, 2022). "Furthermore, transcriptomic analysis indicated 20 overlapped differentially expressed genes, and Serpin peptidase inhibitor clade C Member 1 (Serpinc1) was downregulated during treatment in vivo, whose expression level was markedly related to metastasis and overall survival of lung cancer patients." (PMID 35992834, 2022). "Therefore, reducing the expression of Serpinc1 may be considered as an effective approach to treat lung cancer." (PMID 35992834, 2022). "We anticipate that further investigation of Serpinc1 and other now-uncovered genes/pathways will help reveal the synergy of nab-PTX and anti-PD-1 antibody in tumor types other than lung cancer." (PMID 35992834, 2022). "Though these studies have not stated clearly the relationship between the Serpinc1 gene and lung cancer, they provide a theoretical basis that it is feasible to assume that Serpinc1 may be a critical gene for the progression, metastasis, and prognosis of lung cancer." (PMID 35992834, 2022).
liver cancer (6 papers, 2021 to 2026). An epithelial or non-epithelial malignant neoplasm that arises from the liver. "A curated panel of 30 LRIs specific to liver cancer was formulated, several of which have known associations with LC, including noteworthy ligands like SERPINC1, GPC3, and receptors such as ERBB3." (PMID 39850635, 2024). "In liver cancer, however, studies have shown that higher SERPINC1 expression is inversely associated with M2‐TYPE macrophages that promote tumour progression." (PMID 38923313, 2024). "Within this panel, we find previously documented liver- and liver cancer-relevant marker gene ligands SERPINC1 and GPC3 LRIs to be specific and unique to liver cancer blood samples and thus serve as potentially potent biomarkers." (PMID 39850635, 2024). "Additionally, it was reported that Serpinc1 may be related to the development of colorectal cancer, breast cancer, head and neck cancer, ovarian cancer, nasopharyngeal cancer, liver cancer, and endometrial cancer, involving the proliferation, migration, and invasion of tumor cells." (PMID 35992834, 2022).
lymphoma (6 papers, 2009 to 2024). A malignant (clonal) proliferation of B- lymphocytes or T- lymphocytes which involves the lymph nodes, bone marrow and/or extranodal sites. "To address this question, we validated eight plasma proteins (IL-17A, F5, FLT4, SFTPB, and GNPTG in lymphoma, TNFSF12, CCL3, and KIT in NSCLC) for response prediction and three plasma proteins (IL36G, SERPINC1, and LTA) for relapse monitoring." (PMID 38349411, 2024).
amyloidosis (5 papers, 2013 to 2024). A disorder characterized by the localized or diffuse accumulation of amyloid protein in various anatomic sites. "SERPINA3 and SERPINC1 specifically have also been associated specifically with amyloidotic disorders: both are increased in CSF in early-stage AD, and SERPINA3 has been confirmed to be a major component of senile plaques and to be involved in defibrillation of amyloid in CAA and AD." (PMID 38191511, 2024).
chronic kidney disease (5 papers, 2015 to 2025). Impairment of the renal function secondary to chronic kidney damage persisting for three or more months. "SERPINC1 is associated with dysfunction of the kidney and chronic renal failure." (PMID 30547763, 2018).
colorectal cancer (5 papers, 2017 to 2024). A primary or metastatic malignant neoplasm that affects the colon or rectum. "The results showed that in both univariate and multivariate analyses, high SERPINC1 expression was associated with poor 5‐year survival after radical resection for colorectal cancer." (PMID 38923313, 2024). "Univariate and multivariate Cox demonstrated that SERPINC1 was significantly associated with 5‐year survival after radical surgery for colorectal cancer (p < 0.001)." (PMID 38923313, 2024). "Analysis of colorectal cancer liver metastasis databases in previous studies has found that SERPINC1 may be associated with colorectal cancer liver metastasis." (PMID 38923313, 2024). "Previous studies have suggested that serpin family C member 1(SERPINC1) is involved in the development of a variety of tumours, but its effect on colorectal cancer progression has been poorly elucidated." (PMID 38923313, 2024). "To investigate the biological function of SERPINC1 in colorectal cancer, we used bioinformatics to predict its function." (PMID 38923313, 2024). "First, the expression of SERPINC1 was corrected using housekeeping genes, and subsequent T‐SNE plots revealed significant differences in the expression of different subsets of SERPINC1 in colorectal cancer tissues." (PMID 38923313, 2024). "According to the median value of SERPINC1 expression, 212 colorectal cancer patients were divided into two groups: high SERPINC1 expression group and low SERPINC1 expression group." (PMID 38923313, 2024). "The result showing that SERPINC1 had an area under the ROC curve of 0.72 for prognostic prediction of colorectal patients, and had high accuracy in predicting the prognosis of patients with colorectal cancer." (PMID 38923313, 2024). "Therefore, in this study, we aimed to provide a potential therapeutic target for the treatment of patients with advanced liver metastases from colorectal cancer by analysing the EMT mechanistic impact of SERPINC1 on the regulation of liver metastasis from colorectal cancer." (PMID 38923313, 2024). "However, there is no further study to clarify the relationship between Serpinc1 and malignant proliferation and liver metastasis of colorectal cancer." (PMID 38923313, 2024).
endometrial cancer (5 papers, 2021 to 2025). Primary or metastatic malignant neoplasm involving the endometrium (mucous membrane that lines the endometrial cavity). "SERPINC1 (serpin family C member 1) was also investigated as a diagnostic biomarker in two studies, but one study reported that it was decreased in endometrial cancer cases versus controls, whilst it was not differentially abundant in the other study." (PMID 40987065, 2025). "Six of them were upregulated in endometrial cancer patients (CLU, SERPINC1, ITIH4, C1RL, APOC3 and DSC1), while ten were downregulated (APCS, C9, APOA1, ALB, APOA4, CFHR1, ITIH2, and ACTB)." (PMID 39194522, 2024). "Quantification of protein expression revealed the upregulation of CLU, ITIH4, SERPINC1, and C1RL in endometrial cancer samples compared to the sera of control subjects." (PMID 34298850, 2021). "Several blood-based protein biomarker candidates for endometrial cancer detection were suggested, including the Apolipoprotein family (APOA1/4, APOC1/2/3, and APOE), Clusterin (CLU), Inter-alpha-trypsin inhibitor heavy chain (ITIH2 and ITIH4), and Antithrombin III (ATR/SERPINC1)." (PMID 39194522, 2024).
endothelial dysfunction (5 papers, 2018 to 2025). In vascular diseases, endothelial dysfunction is a systemic pathological state of the endothelium (the inner lining of blood vessels) and can be broadly defined as an imbalance between vasodilating and vasoconstricting substances produced by (or acting on) the endothelium. "In our study, among differentially expressed proteins were PLG, SERPING1, SERPINC1, APOA2, FGB, A2M, which are related to endothelial dysfunction, coagulation processes and pro-atherogenic alteration mechanisms." (PMID 29755368, 2018).
myeloproliferative disease (5 papers, 2014 to 2024). "No abnormalities were detected in other thrombosis-related genes, including Jak-2 (myeloproliferative neoplasms), F2 (prothrombin G20210A), F5 (Factor V Leiden mutation), SERPINC1 (antithrombin III), and PROC (protein C)." (PMID 39465133, 2024).
acute pancreatitis (4 papers, 2019 to 2025). An acute inflammatory process that leads to necrosis of the pancreatic parenchyma. "Others such as serpin peptidase inhibitor, clade C (antithrombin), member 1 (SERPINC1) have anti-inflammatory properties and have been shown to improve acute pancreatitis in the rat model and may be explored in drug development in AP." (PMID 31211768, 2019).
bacterial sepsis (3 papers, 2009 to 2023). "Anti‐thrombin (AT, SERPINC1) has been investigated as a treatment for severe bacterial sepsis and DIC." (PMID 37534622, 2023).
head and neck cancer (3 papers, 2020 to 2023). A primary or metastatic malignant neoplasm affecting the head and neck. "In addition, serpins were associated with head and neck cancer; in particular, it has been reported that SERPINA1 is associated with tumor progression, while SERPINC1 and SERPINF2 are correlated with a good response to radiotherapy, and these data are in good agreement with our results." (PMID 37371031, 2023).
ischemia (3 papers, 2020 to 2021). A hypoperfusion of the BLOOD through an organ or tissue caused by a PATHOLOGIC CONSTRICTION or obstruction of its BLOOD VESSELS, or an absence of BLOOD CIRCULATION. "CD14 and CystatinC protein levels were independent significant predictors of stress-induced ischemia in the LDL and the HDL subfraction and SerpinC1 and SerpinG1 protein levels in the HDL fraction." (PMID 32704130, 2020).
lung adenocarcinoma (3 papers, 2009 to 2024). A carcinoma that arises from the lung and is characterized by the presence of malignant glandular epithelial cells. "Higher SERPINC1 expression is associated with poor tumour microenvironment in lung adenocarcinoma, naive B cells, plasma cells and type M1 macrophages infiltrated more in patients." (PMID 38923313, 2024). "In a study about lung adenocarcinoma patients, eight TME-related prognostic genes were identified by LASSO regression and random forest algorithm, including the Serpinc1 gene." (PMID 35992834, 2022).
migraine (3 papers, 2021 to 2025). "At the brain‐tissue level, we further validated hub gene associations: in migraine, SERPINC1, ZKSCAN8P1, C12orf76, and PAM were significant across brain regions; in migraine with aura, SERPINC1, ALMS1, ZKSCAN8P1, PAM, and NCF2 were significant." (PMID 41261954, 2025). "SMR and INTACT confirmed the validity of BLM, C12orf76, GPATCH4, PAM, SERPINC1 for migraine, and ALMS1, GPATCH4, NCF2, SLC12A1, ZKSCAN8P1 for migraine with aura." (PMID 41261954, 2025). "The results of the SMR, colocalization, and INTACT sensitivity analyses provided further validation of BLM, C12orf76, GPATCH4, PAM, SERPINC1 as contraindicated drugs’ target genes for migraine, and ALMS1, GPATCH4, NCF2, SLC12A1, ZKSCAN8P1 for migraine with aura." (PMID 41261954, 2025). "For migraine with aura, SERPINC1, ALMS1, ZKSCAN8P1, PAM, and NCF2 were significant (p < 0.05); SERPINC1 was significant in nine regions, with the most pronounced association in the Nucleus accumbens (basal ganglia) (p = 0.014)." (PMID 41261954, 2025).
nasopharyngeal carcinoma (3 papers, 2021 to 2024). A carcinoma arising from the nasopharyngeal epithelium. "In nasopharyngeal carcinoma, the high expression of SERPINC1 was also associated with distant metastasis of NPC." (PMID 38923313, 2024).